BRD4 (bromodomain containing 4)
Diseases named in the same sentence as BRD4 in open-access papers (continued):
Sharing a sentence is not in itself a finding about the gene and the disease.
tumor (continued). "OAd replication requires the recruitment of host transcription factors in tumour cells; in BRD4 inhibitor-treated cells, the absence of specific acetylated cellular histones may shift the location of transcription factors to favor the viral life cycle." (PMID 38279262, 2024). "Therefore, we hypothesized that the BRD4 inhibitor I-BET-762 could reduce HO-1 expression and, consequently, reduce the tumor-promoting polarization of macrophages in KC mice stimulated with caerulein." (PMID 39337472, 2024). "Furthermore, similar to Western blot results of tumor tissues, ARV-MBs + US treatment could effectively reduce the expression of BRD4 and c-Myc in tumor cells." (PMID 39140036, 2024). "More severe transcriptional attenuation of these oncogenes was noted upon BRD4 degradation by ZBC-260, with AU-15330 specifically abolishing expression of additional driver oncogenes, again suggesting a distinct mechanism of action for AU-15330-mediated anti-tumour cytotoxicity." (PMID 34937944, 2022). "We therefore examined whether expression of BRD4 and that of SERPINF1 is correlated in human OC specimens, with the use of a published database containing gene expression profiles for tumor specimens obtained by laser capture and microdissection from 53 patients with high-grade serous OC38." (PMID 36056141, 2022). "In contrast, the PGDO7 POLY-PROTAC bearing an ethylene glycol linker negligibly affected BRD4 protein expression, validating the crucial role of GSH-triggered reduction of the disulfide bond and restoration of the VHL ligand for protein degradation inside the tumour cells." (PMID 35882867, 2022). "PVAX was prepared by encapsulating BRD4 inhibitor (JQ-1) and indocyanine green (ICG) co-loaded tumor cells through a hydrogel matrix, which could simultaneously elicit antitumor immunity and block the PD-L1/PD-1 checkpoint to prevent tumor recurrence and metastasis." (PMID 36733612, 2022). "Indeed, we show that combined inhibition of BRD4 and IL6/8-JAK2 signaling is required to inhibit oncogene expression more completely, reversed the BETi resistance in vitro, and suppress the CRC xenograft tumor growth empowered by CAF in vivo." (PMID 34290255, 2021). "Thus, we confirm that UCHL3 is a deubiquitinase for JAK2-phosphorylated BRD4, whose overexpression in CRC may provide a mechanism to maintain the BRD4 protein abundance in an inflammatory tumor microenvironment." (PMID 34290255, 2021). "SPOP has been shown to participate in diverse cellular processes and plays tumor suppressive and oncogenic roles in PrCa by targeting different substrates for ubiqutination-mediated proteolysis, including AR, steroid receptor coactivator 3 (SRC-3), DEK, TRIM24, BRD4 and Nanog." (PMID 34857003, 2021). "Just like in our study, we observed that BRD4 inhibitor JQ1 or knockdown of BRD4 specifically diminished the mRNA and protein levels of tumor suppressor RCAN1.4 in a time- and dose-dependent manner, which at least in part explains why JQ1 could not achieve good anti-tumour effects in solid tumours." (PMID 32771023, 2020). "Pin1 also catalyzes the isomerization of Pro205 of Brd4 and induces its conformational change through a cis-trans isomerization, which leads to enhanced CDK9 binding to Brd4 and enhanced recruitment of CDK9 to a subset of promoters of Brd4-mediated tumor-promoting genes, including c-MET and MMP9." (PMID 32266261, 2020). "Collectively, these results revealed that BRD4 inhibition-elicited repression of EMT progression and proliferation and inducement of pyroptosis in RCC cells were mediated by NLRP3, and that NLRP3 might function as a tumor suppressor." (PMID 32303673, 2020).
tumor (continued). "The results showed that BRD4 was stained more intensely in tumor samples than in non-tumor samples." (PMID 32303673, 2020). "The inhibition of BRD4, a member of the Bromodomain and ExtraTerminal (BET) family of bromodomain-containing proteins, was recently shown to reduce levels of Androgen Receptor (AR) driven target genes in prostate cancer, and reduce tumor burden in murine models." (PMID 31653272, 2019). "Among the various bromodomain regulators, particularly interesting id BRD4, an epigenetic reader protein in the BET family, which binds to enhancers and super-enhnacers of several genes involved in the control of cell proliferation and involved in tumor cell transcriptional addiction." (PMID 31366128, 2019). "The vaccine can spatiotemporally release tumor-specific antigens and the BRD4 inhibitor JQ1 at the surgical bed in a NIR light-controlled manner, which can simultaneously elicit the antitumor immunity and block the PD-L1/PD-1 checkpoint to prevent tumor recurrence and metastasis." (PMID 29670088, 2018). "Direct suppression of BRD4-NUT and concurrent downregulation of other tumor promoting genes such as EGFR and CDK2 by miR-3140 may potentially overcome resistance to BET inhibitors in NMC cells, although further studies are needed to clarify the acquired resistance of BET inhibitiors." (PMID 29540837, 2018). "Controlling for tumor type and restricting to autosomal protein-coding genes, we identified 22 genes (of 18,061 genes) with significantly differential expression between the BRD4 focal deletion and non-deleted cohorts (q < 0.1 cutoff with Bonferroni correction and at least 2-fold expression change)." (PMID 40112818, 2025). "Importantly, when we compared these genes with those downregulated after JQ1 treatment in UM-SCC-047 (n = 1,243), we discovered a significant negative correlation between tumor-specific gene expression (Log2FC[T/N]) and BRD4 inhibition (Log2FC[JQ1/DMSO]) (R = −0.28, p = 1e-06)." (PMID 41323280, 2025). "Our finding that these focal deletions occur in tumors with larger chromosome 19 amplifications further supports the hypothesis that BRD4 focal deletions serve as a mechanism to fine-tune gene expression, rather than alter a tumor suppressor gene, and is more often observed with recurrent deletions." (PMID 40112818, 2025). "Furthermore, it induced rapid tumor regression (>90%) in RS4;11 xenograft tumors, without significant adverse effects in mice, with a single administration capable of causing complete degradation of BRD4 for more than a day, with induction of cell apoptosis." (PMID 38845697, 2024). "Similarly, BRD4 inhibition led to expression of proinflammatory genes such as Baculoviral IAP Repeat Containing 2 & 3 (BIRC2 and BIRC3), which in turn led to tumor necrosis factor (TNF) production triggering apoptosis in preclinical colon cancer models, boosting anti-tumour immunity." (PMID 36551637, 2022). "The poor clinical outcome associated with the BRD4+/high group in the absence of T-bet+ TILs suggests that BRD4 may promote tumor progression through upregulation of chronic inflammatory pathways marked by the production of proinflammatory cytokines such as IL-1α, IL-1β, and IL-6." (PMID 30029633, 2018). "Unlike other NC markers, such as BRD4::NUTM1 and p63, which are diffusely expressed across most tumor cells, SOX2 is restricted to discrete subpopulations, often located near the tumor margin adjacent to the morphologically normal tissue." (PMID 41266112, 2026). "Considering all tumor types, the mean copy number at CCNE1 was significantly higher in BRD4-deletion samples compared to samples without BRD4 deletions (6.7 vs. 3.1; p = 2.6 × 10−8; Wilcoxon rank-sum test)." (PMID 40112818, 2025). "The treatment of AZD9291 alone did not affect BRD4, APT1, YAP1, and p-YAP1 and MST1 palmitoylation in tumor cells, whereas the treatment of NHWD870 alone reduced the expression of BRD4, APT1 and YAP1 but enhanced YAP1 phosphorylation and MST1 palmitoylation." (PMID 41184230, 2025).
tumor (continued). "In the nucleus, LOXL2 binds specifically to the short isoform of BRD4 (BRD4S) that in TNBC has been recently describe as oncogenic, but not to the long one (BRD4L), which has a tumor suppressive role." (PMID 37937685, 2023). "Although RO6870810 is not without biologic activity against BRD4-NUT fusions, where metabolic responses were observed, such responses did not translate to tumour regressions and were only transient." (PMID 33311588, 2021). "In contrast, knockdown of BRD4 but not of BRD2 impairs NK cell cytolytic responses, suggesting BRD4 as critical regulator of NK cell mediated tumor cell elimination." (PMID 33717143, 2021). "However, whether or not BRD4 in PC is a tumor promoter or suppressor remains controversial." (PMID 32099528, 2020). "Our analysis with chemical inhibitors and gene knockdown also reveals that the integrin-FAK axis and epigenetic network (BRD4 and HDAC) cooperatively promote tumor cell survival, but not cell cycle progression." (PMID 32793596, 2020). "Hence, BRD4+/high tumors in the absence of T-bet+ TILs may exhibit BRD4-mediated upregulation of Jagged1 that may induce Jagged-1-Notch1-mediated accumulation and activation of MDSCs, and suppress the infiltration and anti-tumor activity of T-bet+ T cells." (PMID 30029633, 2018). "The combined effects of BRD4 and CDK9 inhibition on blocking tumor cell proliferation might be independent of the MYC- expression, as H1792 is a MYC-amplified cell line and HeLa cells do not harbour any MYC alteration." (PMID 29156698, 2017).
infection (39 papers, 2013 to 2025). The state of being infected such as from the introduction of a foreign agent such as serum, vaccine, antigenic substance or organism. "Inhibition of Brd4 or elimination of Brd4-mediated BIRC3 eRNA synthesis suppressed infection-associated apoptosis resistance." (PMID 32820150, 2020). "It would be of great interest to determine whether inhibition of Brd4 could be a general approach to eliminate pathogen-infection-associated apoptosis resistance." (PMID 32820150, 2020). "By analyzing comprehensive time-course RNA-seq datasets from M. fortis and murine models at various post-infection intervals, we characterized the dynamic transcription patterns of BRD4." (PMID 40616163, 2025). "Conversely, in mice, as infection progresses, the BRD4 transcription level begins to decline around 10 DPI and continues to decrease until approximately 28 DPI." (PMID 40616163, 2025). "These patterns suggest a potential regulatory role for BRD4 in mediating hepatic inflammation during infection." (PMID 40616163, 2025). "BRD4 interactome analysis has uncovered approximately 100 proteins that are enriched in the BRD4 complex and responsive to respiratory syncytial virus (RSV)-infection and BRD4 inhibition, which is related to the BRD4’s acetyl-lysine binding bromodomains." (PMID 37686037, 2023). "In fact, the E2:BRD4 complexes are visible as distinct dots on the mitotic chromosome after successful infection." (PMID 36298829, 2022). "Concordantly, BET bromodomain inhibitors reduced viral transcription upon HPV11 infection, also demonstrating that Brd4 is an activator at this stage of infection." (PMID 34386523, 2021). "The most widely accepted current model contemplates that after infection of the cell by papillomavirus, BRD4 tethers the viral genome to active cellular chromatin to allow viral transcription." (PMID 34439792, 2021). "A subset of infected A549 cells were additionally treated with the BRD4 inhibitor ZL0454 (10 μM) beginning 12 h before infection." (PMID 33799525, 2021). "We observed that Brd4 deletion or inhibition profoundly impairs the clonal expansion and effector differentiation during acute infection due to the reduced glucose uptake." (PMID 34512660, 2021). "Chromatin immune precipitation studies suggested the recruitment of BRD4 at the enhancer loci of miR146a-5p gene during infection." (PMID 33630975, 2021). "Because host innate immunity defends against infection with both DNA and RNA viruses, we investigated the role of BRD4 inhibition in innate immune activation." (PMID 32208449, 2020). "Although PRV infection elevated the expression of IFN-β mRNA, the mRNA and protein expression of BRD4 were normal at 0, 3, 6, 12 and 24 h post-infection (hpi)." (PMID 32208449, 2020). "After infection, the cells had increased NF-κB-dependent BRD4 expression, which promoted the expression of inflammatory factors and ultimately induced macrophage senescence via the autocrine pathway." (PMID 32392533, 2020). "We found that suppression of BRD4 expression or inhibition of P-TEFb activity blocked Ad infection, indicating that Ad exploits gene transcription mechanisms for productive infection and transgene expression." (PMID 30068949, 2018). "The results suggested to us that both Ad infection and JQ1 effect on the infection required BRD4 protein expression." (PMID 30068949, 2018). "Another study demonstrated that Brd4 is capable of directly activating HPV-18 transcription during early stages of infection in an E2-independent manner, indicating that Brd4 plays a central role in the dynamics of viral expression." (PMID 30328948, 2018). "The remaining 6 compounds increasing infection include histone lysine-methyl binding proteins, prolyl hydroxylase inhibitors, and chromatin-associated bromodomain family member BRD2/BRD4 inhibitors." (PMID 28114951, 2017). "The quasivirus infection system was used to determine the role of the Brd4 protein in the earliest steps of HPV infection." (PMID 27879331, 2016).
infection (continued). "In this study, we have optimized HPV18 quasivirus production and infection of primary keratinocytes and have used the system to identify the role of the Brd4 chromatin adaptor protein in viral transcription and replication at very early stages of infection." (PMID 27879331, 2016). "Thereafter, we used this system to study the role of Brd4 upon initial infection, a relatively understudied phase of the infectious cycle." (PMID 27879331, 2016). "We demonstrate that Brd4 activates early viral transcription upon infection and does so in an E2-independent manner." (PMID 27879331, 2016). "Using siRNA to downregulate Brd4 expression, we show that Brd4 activates HPV18 transcription at early stages of infection." (PMID 27879331, 2016). "In this study, we further optimize and utilize a quasivirus infection system to show that Brd4 activates HPV18 transcription at early stages of infection." (PMID 27879331, 2016). "One explanation for these findings is that the interaction of E2 and BRD4 is important to establish an efficient infection when limiting amounts of genome are delivered to the nucleus by a viral particle rather than by DNA transfection." (PMID 24832099, 2014). "We have previously proposed that Brd4 tethers the viral genome to host chromatin at early stages of infection to regulate viral transcription and ensure that the genome is located in active regions of the nucleus." (PMID 24278023, 2013). "Next, we addressed whether JNK was required to mediate infection-induced BRD4 release since a recent report showed that JNK was required to modulate anisomycin-induced BRD4 release for transcriptional regulation." (PMID 40812420, 2025). "Islet organoids were infected via lentiviral BRD4 shRNA with a GFP as an infection tracking marker." (PMID 40539402, 2025). "To further elucidate the potential role of BRD4 in the anti-parasitic process, we employed the fuzzy c-means clustering algorithm to categorize genes with transcriptional profiles congruent with that of BRD4 throughout the time course of infection." (PMID 40616163, 2025). "These two studies support the concept that BRD4 may be a target in cigarette smoke- and infection-exacerbated COPD." (PMID 37686037, 2023). "Further, cIAP-levels may be concurrently up-regulated by other signalling pathways, such as canonical NF-κB or, as recently shown for cIAP2 and Hp-infection, through Brd4." (PMID 35505004, 2022). "Moreover, there was an approximately 5-fold reduction of memory P14+CD8+ T cells at day 35 post-infection upon Brd4 deletion." (PMID 34512660, 2021). "Small Interference RNA (siRNA) infection was used to silencing BRD4 or TREM1." (PMID 33446277, 2021). "Patients receiving Brd4 inhibitors could cause attenuated antiviral immunity, due to the potential defective CD8+ T cells response to infection." (PMID 34512660, 2021). "Of the 227 BRD4 interactors that were recruited to the BRD4 complex during RSV-infection, we observe that 95 ( 42%) are disrupted to some degree by treatment with ZL0454, including most of the transcription factors described in the earlier section (e.g., c-JUN, CTNNB1, JUP, DDX3X, MTDH)." (PMID 33799525, 2021). "Thus, Brd4 is an activator of viral transcription at very early stages of infection before the E2 protein is expressed and converts Brd4 to a transcriptional repressor." (PMID 34386523, 2021). "BRD4 inhibition leads to viral arrest in infection by different types of viruses." (PMID 34439792, 2021). "However, because of the difficulties in producing HPV viral particles, the role of Brd4 in modulating viral transcription and replication at the initial stage of infection is unclear." (PMID 27879331, 2016). "Here, we show that HPV18 viruses encoding E2 proteins unable to bind Brd4 can replicate efficiently, indicating that interaction with chromatin is not essential at this early stage of infection." (PMID 27879331, 2016).